ZNF137P (zinc finger protein 137, pseudogene)
Description:
May be involved in transcriptional regulation.
Synonyms: pHZ-30; formerly ZNF137
Gene: Transcribed unprocessed pseudogene on chromosome 19 (52,588,551 to 52,597,413, forward strand). Ensembl gene ENSG00000123870.
Subcellular location: Nucleus
Diseases named in the same sentence as ZNF137P in open-access papers:
ZNF137P is named in the same sentence as 3 diseases in open-access papers, as found by Europe PMC text mining. Sharing a sentence is not in itself a finding about the gene and the disease. The quoted sentences say what the papers report.
infection (1 paper, 2015). The state of being infected such as from the introduction of a foreign agent such as serum, vaccine, antigenic substance or organism. "While pseudogene ZNF137P is increasingly downregulated as the infection progresses, its parent gene ZNF83, an anti-inflammatory gene, is over-expressed by a factor of 1.5 in all six datasets at 24 h post-infection, but is under-expressed seven days post-infection." (PMID 26426037, 2015).
ZNF137P also shares sentences with these, for which no sentence is quoted: HIV-1 infection (1 paper); lung adenocarcinoma (1).